IL2 (interleukin 2)
Diseases named in the same sentence as IL2 in open-access papers (continued):
Sharing a sentence is not in itself a finding about the gene and the disease.
tumor (continued). "However, in situ production of IL-2 and IL-15 is necessary to continually reactivate infiltrating NK cells to prevent NK cell exhaustion and inhibition by the tumour milieu suppressor cells and humoral factors, such as TGF-β." (PMID 26040463, 2015). "The results show that the TGF-β inhibitor and IL-2 reduced tumor growth." (PMID 26078967, 2015). "These treatments result in good outcomes, which may not only be due to a direct kill of the tumor cells by IL-2 but also be because the fever as its “side-effect” may enhance the efficacy of the other agents." (PMID 26495849, 2015). "Additional benefit may be gained with use of immune modulating adjuvants such as anti-PDL-1, anti-CTLA-4, GM-CSF, or IL-2 to overcome tolerance and optimize anti-tumor immunity." (PMID 25933160, 2015). "Compared with IL-2-mediated activation, NK-cell expansion in the presence of feeder cells may also result in increased anti-tumor cytotoxic functions, with comparable in vivo survival." (PMID 26029215, 2015). "Characterization of cytokine expression patterns in these accumulated myeloid splenocytes in tumor bearing mice revealed a Th2 dominant pattern with decreased IL-2, IL-12, interferon (IFN)-γ and tumor necrosis factor (TNF)-α and elevated IL-4 and transforming growth factor (TGF)-β." (PMID 26690220, 2015). "In the treatment of solid tumors, the initial administration of n-BP/IL-2 followed by infusion of bispecific antibody together with IL-2 could probably enhance cytotoxic activity of γδTc, which infiltrate several different tumor types at low frequency." (PMID 25566256, 2014). "An interferon γ and interleukin 2 enzyme-linked immunosorbent assay and a chromium-51 release assay were used to evaluate the antitumor immune response of CAR T cells in coculture with tumor cells." (PMID 24919843, 2014). "However, in murine tumor models GM-CSF and IL-2 were shown to act synergistically when applied intradermal in emulsion along with a peptide, leading to improved and long-lasting peptide-specific CTL responses." (PMID 24782858, 2014). "Thus, it was proposed that tumor exosomes contribute to the growth of tumors by blocking IL-2-mediated activation of NK cells and their cytotoxic response to tumor cells." (PMID 24639679, 2014). "Gene therapy studies, involving tumor modification for production of inflammatory cytokines (e.g. IL-2) to enhance tumor immunogenicity as well as with IL-12-expressing DNA plasmids to slow tumor growth and stimulate a robust CTL response, have also utilized the GL261 model." (PMID 24779345, 2014). "Conversely, in the HER2-negative cohort, which is different from the HER2-positive arm for the biology of the tumor, the NC treatment, and also for the immune profile at diagnosis, we observed changes in IL-1α, IL-1β, IL-2, IL-6, and GM-CSF levels already at week 12 of ED treatment." (PMID 25512030, 2014). "IL-2 in combination with Treg depletion generated “hyperactivated” NK cells with enhanced antitumoral activity and secreting factors that facilitated oncolytic virus spread throughout the tumor by disrupting the tumor architecture." (PMID 25101244, 2014). "Thus, liposomes functionalized with co-stimulatory signals for T-cells such as 4-1BBL and immune stimulatory cytokines such as IL-2 have been used to prime T-cells to induce an anti-tumor response." (PMID 25380524, 2014). "IL-2 or IFN-γ may induce NK cell-induced tumor death and IFN-γ directly causes DNA fragmentation of tumor cells, which demonstrates that Th1 cells present a powerful status against tumors." (PMID 24520300, 2014). "In this study, using a lipophilic, NIR-fluorescent cyanine cell membrane dye and a direct labeling method, we investigated the tumor localization and migration of 4T1 tumor specific T-lymphocytes that were first activated in vitro with Bryostatin/Ionomycin (B/I) and grown with Interleukin-2 (IL-2)." (PMID 25334026, 2014).
tumor (continued). "As heavy-ion beam irradiation removed the tumor burden of tumor-bearing golden hamsters, the secretion of sIL-2R was reduced by blocking tumors to the activation of T lymphocytes; however, the content of IL-2 increased." (PMID 24748984, 2014). "Jurkat cells transduced with a TCR specific for Melan-A/MART-1 showed increased IL-2 production when co-cultured with iHsp90-treated tumors than with untreated (control) tumor cells, as an indication of enhanced T cell recognition as a consequence of inhibited Hsp90 function." (PMID 25503774, 2014). "In addition, adoptive infusion of HSP70/IL-2 pre-stimulated NK cells induced shrinking of tumor masses in tumor-bearing mice and improved survival." (PMID 25356750, 2014). "To further characterize the immunologic mechanisms behind the anti-tumor effects of IL-2-based immunotherapy and the role of CD4+ T cells in antigen non-specific bystander expansion, we analyzed the phenotype and function of the proliferating CD8+ cells after IT in the absence of CD4+ T cells." (PMID 25119341, 2014). "Similarly, splenocytes secreted more IL-2 in response to tumor lysates or β-galactosidase than in response to ovalbumin." (PMID 25340750, 2014). "Notable exceptions include interferon (IFN)-α2b (also known as Intron A®), and IL-2 (also known as aldesleukin and Proleukin®), which mediate single agent therapeutic activity in patients affected by melanoma, a tumor type particularly sensitive to immunotherapy." (PMID 25537519, 2014). "Clear cell histology of the primary tumor was associated with a higher response rate to HD IL-2 when compared with patients with non-clear cell histology." (PMID 25562142, 2014). "In order to identify the roles of IL-2 and IL-15 during induction of tumor toxic function of CIK cells, we performed comparative transcriptome analysis between CIK cells prepared with IL-15 and IL-2 respectively by Ion PI mRNA sequencing (RNA-seq) for the first time." (PMID 25108500, 2014). "Tumoral cells act through cell-cell contacts and cytokine secretion to provoke an excessive T cell suppression, abnormal response to interleukin-2, and downregulation of immunoglobulin secretion by NK cells, which culminates in a failure in B lymphocytes regulation and decreased antibody production." (PMID 24551464, 2014). "Furthermore, the addition of IL-7 or IL-15 was shown to abrogate the suppressive activity of Tregs in vitro and the administration of anti-IL-2 plus exogenous IL-15 to tumor-bearing mice enhanced the adoptive immunotherapy of tumors." (PMID 24748966, 2014). "A number of immune cells have been isolated from RCC, including natural killer (NK) cells, cytotoxic T cells with specificity for autologous tumor cells, helper T cells and dendritic cells that express interleukin (IL)-1 and IL-2 and function as antigen-presenting cells." (PMID 24348776, 2014). "The 4-1BB costimulated post-REP CD8+ TIL could also expand further with IL-2, exhibited enhanced ability to kill tumor targets, and expressed increased bcl-2 expression." (PMID 23560068, 2013). "However, low concentration of IL-2 was failed to induce adequate amount of immune cell cytotoxicity towards tumor regression while high concentration of IL-2 can produce a severe lymophopenia and toxic side effect." (PMID 23800124, 2013). "For example, is has been suggested that Tregs may promote apoptosis of antitumor effector cytotoxic T cells by depleting the tumor milieu from IL-2, a T cell survival cytokine." (PMID 23533456, 2013). "The resulting L19-IL-2 fusion product might be an attractive concept to enhance therapeutic effects of IL-2 by directly conjugating IL-2 to the tumor site." (PMID 24303367, 2013). "In addition, the tumor was converted into an immunostimulatory environment characterized by a Th1 profile in which several cytokines were upregulated, including IL-2, IL-1, IFN-γ and TNF-α." (PMID 23441198, 2013).
tumor (continued). "Indeed, in contrast to mNK cells, IL-15-stimulated pre-mNK cells show an improved response to type 1 IFN and IL-2 facilitating their migration into tumor beds in a CCL2-dependent manner." (PMID 24376447, 2013). "The creation of a favorable host anti-tumor immune microenvironment by in situ delivery of interleukin-2 (IL-2) and granulocyte macrophage colony growth factor (GM-CSF) genes into the peri-tumoral site resulted in improved radio-responsiveness and systemic anticancer immunity." (PMID 23634213, 2013). "IL-2 has been identified as the NK cell immunomodulator in tumor immunotherapy." (PMID 23800124, 2013). "Likewise, the release of IL-2 promoted significant activation of CTL in an autocatalytic immunological cycle that finally inhibited tumor growth." (PMID 24350772, 2013). "Current methodology for the expansion of T cells for ACT involves the expansion of TIL from small tumor fragments or biopsies by exposure to IL-2, irradiated allogeneic feeder cells and CD3 ligation via an anti-CD3 antibody, a process called rapid expansion method (REM)." (PMID 23402380, 2013). "In the transition rate calculations, the variable TotalTumour corresponds to the total number of tumour cell agents; the variable TotalEffector is the total number of effector cell agents, TotalIL_2 is the total number of IL-2 agents and TotalTGF Beta is the total TGF-β agents." (PMID 23734575, 2013). "However, in our large established tumor model where animals die at an early time point, we were unable to evaluate the long-term antitumor memory effects of IL-15 vs. IL-2." (PMID 24391824, 2013). "Moreover, existing clinical evidence suggests the combination of low-dose cyclophosphamide together with a continuous-infusion or IL2 or other related biologics yields significant anti-tumor activity in patients with advanced cancers." (PMID 23320927, 2013). "To test this hypothesis, we adoptively transferred anti-4-1BB Abs into tumor-bearing animals following treatment with the E7 DNA vaccine regimen {E7 DNA vaccines (pE7)+IL-2 cDNA (pIL-2)}." (PMID 24391824, 2013). "Adoptive transfer of ex vivo expanded autologous tumor-infiltrating lymphocytes together followed by one to two cycles of high-dose IL-2 therapy has emerged in multiple Phase II clinical trials to be one of the most powerful therapies for unresectable metastatic melanoma." (PMID 23560068, 2013). "It is important to note that studies since the late 1980s have demonstrated the reversal of these tumor-associated NK cell traits after a few days of ex vivo culturing alone or with IL-2, suggesting the absence of any inherent NK cell defect per se." (PMID 24324471, 2013). "Moreover, the NK-mediated autophagy induction in target cells was enhanced by provision of IL-2 and cell-cell interactions between NK cells and tumor cells." (PMID 24400010, 2013). "EMD 521873 (Selectikine or NHS-IL2LT) is a fusion protein consisting of modified human IL-2 which binds specifically to the high-affinity IL-2 receptor, and an antibody specific for both single- and double-stranded DNA, designed to facilitate the enrichment of IL-2 in tumor tissue." (PMID 23294527, 2013). "IL2 therapy was given along with dTc for some groups because IL2 is known to enhance T cell function and may play a role in tumor clearance." (PMID 23433424, 2013). "Indeed, the adoptive transfer of IM and IL-2-stimulated pre-mNK cells dramatically impaired melanoma tumor outgrowth in immunodeficient (Rag2−/−Il2rg−/−) mice." (PMID 24376447, 2013). "Lymphodepletion can eradicate suppressive immune cells in the host, including Tregs and myeloid-derived suppressor cells, and the repopulation of tumor-specific effector T cells significantly exceeded that of Tregs, as the expansion of Tregs was limited by interleukin (IL)-2 availability." (PMID 24403229, 2013).
tumor (continued). "However, the addition of anti-4-1BB Abs to the E7 DNA vaccine regimen (E7 DNA vaccines+IL-2 cDNA) increased the tumor cure rate from 27% to 67%, a 9.6-fold increase in tumor cure rates following the addition of both IL-2 cDNA and anti-4-1BB Abs." (PMID 24391824, 2013). "Since IL23 is involved in the induction of inflammatory diseases which may contribute to tumor progression, however, a combination of those cytokines with other pro-inflammatory cytokines like IL2 needs to be carefully designed." (PMID 23028547, 2012). "A possible explanation to this observation is that the mouse BW cells express an unknown tumor ligand for the mouse NCR1 which consistently triggers IL-2 secretion as BW cells are specifically recognized by NCR1-Ig (data not shown)." (PMID 22457623, 2012). "In order to determine if NKG2D-Fc-IL2 can bind to NKG2D ligand-expressing tumor cells while preserving the IL-2 functionality of promoting T cell proliferation, we incubated NKG2D-Fc-IL2 with irradiated MOSEC tumor cells, alongside equivalent assays with relevant control proteins." (PMID 22509395, 2012). "Indeed, up to now immunotherapy using interleukin-2 and interferon-γ is the most used pharmacological approach for this kind of neoplasia." (PMID 23144690, 2012). "Based upon the ability of IL-2 to strongly induce OX40 in vitro, we sought to evaluate whether the provision of IL-2 in conjunction with anti-OX40 mAb therapy would augment anti-tumor immunity in vivo." (PMID 22496812, 2012). "Thus, a strategy that is able to specifically deliver IL-2 to the tumor location will significantly reduce the required amount of administered IL-2, alleviating many of the side effects commonly associated with its systemic administration." (PMID 22509395, 2012). "We reason that the specific delivery of IL-2 to the tumor loci may enhance the proliferation of tumor specific CD8+ T cells in the tumor microenvironment." (PMID 22509395, 2012). "Furthermore, we were able to use the NKG2D-Fc protein to deliver both a marker protein (GLuc) and IL-2 to the tumor loci in tumor-bearing mice." (PMID 22509395, 2012). "In order to determine if the NKG2D-Fc protein could be used to deliver IL-2 to the tumor loci, we linked NKG2D-Fc to IL-2, generating the chimeric NKG2D-Fc-IL2 protein." (PMID 22509395, 2012). "These calcineurin inhibitors act by reducing interleukin-2 expression, inhibit the early activation of T lymphocytes (that is, the transition from the G0 to the G1 phase of the cell cycle) and promote tumor cell cycle progression by increasing cdk4 kinase activity." (PMID 22721369, 2012). "Furthermore, combined treatment with an agonist anti-OX40 mAb and IL-2 augmented tumor immunotherapy against multiple tumor types." (PMID 22496812, 2012). "Similar to TILs, stimulation with anti-CD3 and IL-2 restored cytotoxicity against tumor cells." (PMID 23118782, 2012). "Thus the data suggest the chimeric NKG2D-Fc-IL2 technology has potential to be used to further enhance the therapeutic anti-tumor effect generated by the therapeutic HPV DNA vaccine." (PMID 22509395, 2012). "First, we confirmed whether IL-2 stimulation was capable of up-regulating OX40 in vivo on CD8 T cells in tumor-bearing mice." (PMID 22496812, 2012). "Additionally, IL-12 gene therapy against CC has been used in conjunction with other cytokines such as GM-CSF and IL-2, resulting in an increase of the protective effect against tumor growth." (PMID 22220169, 2012). "More importantly, we demonstrated that IL-2 linked to NKG2D-Fc led to significant proliferation of the tumor-specific CD8+ T-cell at the tumor loci and resulted in potent therapeutic anti-tumor effects in TC-1 tumor-bearing mice that received the therapeutic HPV16/E7 DNA vaccine." (PMID 22509395, 2012). "Failure to produce or recognize IL-2, results in impaired tumour lyses." (PMID 23346250, 2012).
tumor (continued). "Furthermore, the IL-2 component of the chimeric protein was capable of inducing proliferation of T cells in vitro and at the tumor site in vivo." (PMID 22509395, 2012). "IL-2 treatment induced a modest reduction of tumor weight (<10%)." (PMID 22303460, 2012). "For example, genetically modified mesenchymal or neural stem cells overexpressing interleukin-2 or interleukin-12 may be used to inhibit tumor growth." (PMID 22253739, 2012). "Moreover, IL2+resveratrol co-treatment was more effective in inhibiting tumor metastasis than IL-2 treatment alone." (PMID 22532866, 2012). "Given the ability of IL-2 signaling to regulate OX40 expression in vitro and in vivo, we hypothesized that treatment with an agonist anti-OX40 mAb in conjunction with IL-2 would augment tumor immunotherapy." (PMID 22496812, 2012). "Therefore, spleen cells were stimulated with irradiated 4T1 tumor cells for 5–8 days in the presence of IL-2 (300 IU/mL)." (PMID 22654951, 2012). "Therefore, we combined MRF/magnet treatment with anti-CD40/IL2 to treat disseminated disease and determine if greater anti-tumor responses and systemic immune activation can be achieved with this multi-approach therapy." (PMID 23133545, 2012). "Therefore, we believe that our findings that MUC1-specific Treg cells suppress IL-2 production from MUC1-specific CD4+ T cells provide important information in tumor immunity." (PMID 23028615, 2012). "Results from a phase I study of stereotactic body radiation therapy (SBRT) and systemic IL-2 in melanoma and renal cell carcinoma demonstrated that this combination could result in impressive responses in both tumor types." (PMID 23087904, 2012). "Additionally, inhibition of tumor growth was observed significantly in mice following vaccination with AFP/IL-2-DC compared with mice vaccinated with other vaccines (P<0.01)." (PMID 23170121, 2012). "Both responding patients had gone through extensive surgery and had, at the time of treatment initiation, only limited disease burden, suggesting that debulking of tumor-mass may play a role for the outcome of TIL therapy using low-dose IL-2." (PMID 22909342, 2012). "IL-15 has even been shown to be more effective than IL-2 for tumor growth inhibition." (PMID 22509395, 2012). "Therefore, by linking NKG2D to IL2, we are able to specifically deliver IL-2 to the tumor location, enhancing antigen-specific T-cell immune response and controlling tumor growth." (PMID 22509395, 2012). "Results showed that 30 days of β-carotene treatment could significantly inhibit tumour growth, enhance blood NK, IL-2, TNF-α, WBC, TP, ALB and A/G levels, and decrease blood ALT, AST and ALP activities in HCC rats." (PMID 22810193, 2012). "Taken together, tumor-exosomes inhibit Th expansion/activation in response to IL2." (PMID 23190502, 2012). "Moreover, this efficacious response was recapitulated in the same tumor model using i.v. administration of reovirus combined with IL-2 and cyclophosphamide (CPA)." (PMID 22312364, 2012). "Here, we show that NKG2D-Fc-IL2 was able to bind to murine NKG2D ligand-expressing tumor cells." (PMID 22509395, 2012). "Furthermore, we detected the expression of IL-2 and IL-12p70 in the peripheral blood of tumor-bearing mice." (PMID 21963624, 2011). "Moreover, some of these expanded tumor-infiltrating lymphocyte (TIL) populations were re-injected in patients together with IL-2 and produced objective tumor responses." (PMID 24212939, 2011). "IFN-γ may also be an important regulator of anti-tumor activity mediated by other cytokines, in particular IL-12 and probably IL-2." (PMID 24213115, 2011). "Importantly, our in vitro experiments reveal a significant increase of hI-con1-induced cytotoxicity after the brief incubation of PBL and tumor cells with IL-2 compared to the cytotoxicity induced by hI-con1 in the absence of IL-2." (PMID 21693061, 2011).